IL6 (interleukin 6)
Diseases named in the same sentence as IL6 in open-access papers (continued):
Sharing a sentence is not in itself a finding about the gene and the disease.
breast cancer (continued). "Breast cancer cells stimulate surrounding adipose stromal cells to produce aromatase, an enzyme responsible for oestrogen synthesis, by releasing factors such as IL-6 and Prostaglandin-E2." (PMID 39682099, 2024). "For example, FOSL1 has been reported to upregulate the expression of IL-6 in breast cancer cells, which can promote tumor growth and invasion by activating the STAT3 signaling pathway." (PMID 38791400, 2024). "BRCA1, MYC and IL-6 were identified as the top three hub genes in infected-breast cancer cells based on the connectivity of PPI analysis." (PMID 38654350, 2024). "We proceeded with the TNBC subtype due to a greater increase in tGAS+IL-6/IL-6R/GP130 co-activation in TNBC patients when compared to the HER2-enriched breast cancer subtype." (PMID 39768178, 2024). "MCF-7 belongs to the human HRP + -breast cancer cell line, and IL-6 significantly enhances its invasiveness with a low concentration, leading to an increased risk of death in patients." (PMID 39108599, 2024). "Numerous studies have highlighted the critical importance of interleukins, particularly IL-1, IL-6, and IL-8, in promoting bone metastases from breast cancer through different signaling pathways." (PMID 39125732, 2024). "Polysaccharide peptide (PSP) acts by upregulating the TLR4-TIRAP/MAL-MyD88 signaling pathway in peripheral blood mononuclear cells (PBMCs) from breast cancer patients, inducing the secretion of IL-12, IL-6, and TNF-α, thus serving as an immune adjuvant." (PMID 38347830, 2024). "MiR-203 directly inhibits the SOCS pathway in MCF7 cells which suppresses breast cancer progression while miR-7 directly binds to 3′-UTR of IL-6 to negatively regulate its expression which results in antitumorigenic and antimetastatic effects in breast cancer." (PMID 38726321, 2024). "Proinflammatory cytokines IL-6 and IL-8 and anti-inflammatory cytokine IL-10 play vital roles in breast cancer progression." (PMID 38314029, 2024). "Dysregulated IL-6/IL-6R/GP130 signaling promotes breast cancer cell proliferation, breast CSCs, and therapeutic resistance, contributing to tumor recurrence." (PMID 39768178, 2024). "IL-6/JAK/STAT3 pathway leads to EMT activation not only in breast cancer but also in cervical carcinoma." (PMID 38892394, 2024). "The GPR30 antagonist G15 and the Gα inhibitor PTX reduced these properties, supporting the GPR30 role in the metastatic phenotype induced by IL-6 in breast cancer." (PMID 39201674, 2024). "Collectively, our data identified OSM/IL-6/JAK as a clinically relevant paracrine/autocrine axis instigating breast cancer cell plasticity and triggering metastasis." (PMID 38236642, 2024). "IL-6 has recently been found to mediate the relationship between survival after breast cancer and CRCI." (PMID 38840166, 2024). "Using the provided MFS information in the curated GEO breast cancer patient dataset used in, breast cancer patients were stratified by high versus low tGAS and IL-6/IL-6R/GP130 activation scores." (PMID 39768178, 2024). "The scRNA Seq dataset analysis also confirmed the positive correlation between Wdr5 and PD-1, PD-L1, and Spp1, as well as the positive correlation between Wdr5 and both TGFβ and IL6 in both human colon cancer and human breast cancer." (PMID 39201460, 2024). "Training programs with Taichi 120 min a week for 3 and 4 months, respectively, are reportedly to show the trend to decrease TNF-α and IL-6 in breast cancer survivors with insomnia and in older adults with insomnia." (PMID 38635535, 2024). "Lactic acid bacteria have been found to reduce Stat3 expression and secrete IL-6, thereby inhibiting breast cancer stem cells, suggesting their potential in breast cancer treatment and prevention." (PMID 39360320, 2024). "The constitutive expression of Twist in breast cancer cells can result from inappropriate production of IL-6 and STAT3 phosphorylation." (PMID 38519574, 2024).
breast cancer (continued). "Conversely, breast cancer patients with high tGAS and high IL-6/IL-6R/GP130 activation scores had a significantly shortened MFS at a dismal 22.1 months." (PMID 39768178, 2024). "For instance, studies identified higher levels of serum IL-6 in breast cancer patients compared to healthy individuals." (PMID 38339245, 2024). "A similar phenomenon can be observed in correlation between Wdr5 and both TGFβ and IL6 in both human colon cancer and human breast cancer in myeloid cells, cancer epithelial cells, and T cells." (PMID 39201460, 2024). "Further examination of the blocking activity showed that they exhibited a significant inhibition of IL-6-enhanced migration on the human breast cancer cell MCF-7." (PMID 39108599, 2024). "In breast cancer, an increase in IL6 secretion from TAMs promoted expression of SOX2, OCT4, and NANOG." (PMID 39287565, 2024). "IDO1 is highly expressed and promotes metastasis, drug resistance, cell proliferation, and TAM resistance through STAT3 and interleukin-6 in TAM-resistant breast cancer." (PMID 38539263, 2024). "IL-6 induces metastasis and angiogenesis and promotes myeloid cell recruitment in breast cancer via activation of an IL-6/Jak1/2/STAT3 signaling pathway." (PMID 38360812, 2024). "This IL-6 signaling pathway positively interacts with the Stat3 pathway, resulting in tumor promotion and an increase in breast cancer stem cells, mainly in the triple-negative subtype." (PMID 38813102, 2024). "In invasive HER2+ breast cancer, IL-6 and IL-8, which are the core inflammatory factors in the SASP, are related to the stemness of CSCs." (PMID 38540708, 2024). "While IL-6 treatment leads to aromatase activation in endometrial and breast cancers, in dermal fibroblasts, IL-6 and E2 increased CYP19A1 transcript levels, suggesting increased aromatase activation." (PMID 39000334, 2024). "Collectively, our results demonstrate that tGLI1 and IL-6/IL-6R/GP130 signaling pathways are frequently co-overexpressed and co-activated and that co-activation is associated with worse MFS in HER2-enriched breast cancer and TNBC." (PMID 39768178, 2024). "ETBF infection can also trigger systemic inflammation in breast cancer, increasing the levels of proinflammatory and tumorigenic cytokines such as IL-17A and IL-6." (PMID 39926112, 2024). "Breast cancer patients with low tGLI1 and IL-6 pathway activity, as indicated by low tGAS and low IL-6/IL-6R/GP130 activation scores, had a prolonged MFS at 55.0 months." (PMID 39768178, 2024). "Specifically, Interleukins (ILs) such as IL-6, IL-8, IL-1β, and IL-11 have been identified as important regulators in the onset and advancement of breast cancer spreading to the bones." (PMID 39125732, 2024). "The GPR30 antagonist G15 or PTX toxin, a G-protein (αi) inhibitor, inhibited all the proliferative effects, suggesting the GPR30 participation in the proliferation stimulated by E2 and IL-6 in breast cancer cells." (PMID 39201674, 2024). "The role of IL-6 in dormancy reactivation is further supported by evidence from DTC samples in the bone marrow of breast cancer patients and CD133+ stem-like cells." (PMID 39682769, 2024). "In preclinical studies, Palbociclib-resistant breast cancer cells demonstrated upregulation of the IL-6/STAT3 pathway, and treatment with TTI-101 significantly increased cell death." (PMID 38339245, 2024). "In the present study, we used Bazedoxifene (DUAVEE®; BZA), which directly binds the GP130 receptor to inhibit IL-6-induced STAT3 activation in breast cancer." (PMID 39768178, 2024). "The previous results of animal experiment demonstrated that PVL-TH increased the level of interleukin-6 (IL-6) in breast cancer model mice, inhibiting the growth and promoting the apoptosis of breast cancer cells." (PMID 39840098, 2024). "Extensive research has substantiated the immunopathogenic role of IL-6 and its signaling pathway in breast cancer, influencing growth, metastasis, and drug resistance." (PMID 39738201, 2024).
breast cancer (continued). "Since dual-targeting tGLI1 and GP130 suppresses metastatic burden and prolongs MFS in vivo, we next wanted to examine the clinical relevance of tGLI1 and IL-6/IL-6R/GP130 in breast cancer metastasis using publicly available patient datasets." (PMID 39768178, 2024). "We identified a standout nanobody, NbL3, which exhibited high affinity (22.16 nM) and stability and significantly inhibited IL-6-enhanced migration on the human breast cancer cell MCF-7 at a relatively low concentration." (PMID 39108599, 2024). "This work aims to determine the GPR30 role in the metastatic properties induced by IL-6 in luminal breast cancer cells." (PMID 39201674, 2024). "A human breast cancer cell line (MCF-7) responded to kynurenic acid at a physiologically relevant concentration of 100 nanomols/L with an induced expression of IL-6." (PMID 39201726, 2024). "Treatment with breast cancer CM or direct co-culture with breast cancer cells upregulated Rankl, Mmp13, and Il6 and decreased Cthrc1 mRNA expression in MLO and Ocy454 cells." (PMID 38558984, 2024). "In this study, we aimed to explore the therapeutic effects of gold nanoparticles (GNP) against IL-6 overexpression and the modulation of miRNA-26a-5p in breast cancer (BC) cells." (PMID 38338683, 2024). "Specifically, berberine reduces the expression of TNFα and IL-6 as well as inhibits c-Jun, c-Fos and NF-κB signaling in breast cancer cells." (PMID 36670988, 2023). "Further, IL-6 increased the cancer stem fraction similarly to progranulin in the breast cancer cell lines MCF7 and MDA-MB-231 monitored by the surrogate mammosphere-forming assay." (PMID 38136303, 2023). "Based on these results, IL-6, secreted by the adipocytes, promotes breast cancer cell growth and metabolism by upregulating ASCT2 protein expression." (PMID 37894450, 2023). "For example, the upregulation of IL-6 increases tumor invasion and epithelial-mesenchymal transition in human breast cancer cells." (PMID 37238871, 2023). "Transcriptomic data from TEPA treated breast cancer cells also displays changes in the immune-related genes (including IL6, IL6R, IL15, CXCL1, CXCL8, and PTX3) in breast cancer." (PMID 37480151, 2023). "In breast cancer, the IL-6/gp130 pathway is frequently activated, promoting breast cancer metastasis and suppressing the anti-tumor immune response." (PMID 36495330, 2023). "On the other hand, for breast cancer cells cocultured with in vitro differentiated murine adipocytes, a significant increase in IL-6 expression was observed, which elevated checkpoint kinase 1 (Chk1) phosphorylation and promoted radioresistance in tumor cells." (PMID 36670988, 2023). "After the activation of PI3K/AKT in the breast cancer cells, the expression of IL-6, IL-1β, and tumor necrosis factor-α (TNF-α) in breast cancer cells is increased." (PMID 36624542, 2023). "In a pilot randomized controlled trial with 46 postmenopausal breast cancer survivors, the 3-month exercise intervention resulted in a significant difference in IL-6 between the intervention and control group." (PMID 37181043, 2023). "The contribution of autophagy to the process of bone metastasis in breast cancer is autophagy-mediated IL-6 secretion." (PMID 36831154, 2023). "The MC-38 cell line derived from C57BL/6 murine colon adenocarcinoma cells and 4T1 cell line from BALB/c murine breast cancer can be employed as a robust preclinical immuno-oncology model and expressed PD-L1 and secretory IL-6." (PMID 37924094, 2023). "It has also been found that in vitro VCAM-1 knockdown in breast cancer cells reduces the proliferation and migration of IL-6-influenced breast cancer cells, thus increasing chemosensitivity." (PMID 36793444, 2023). "Genomic DNA samples extracted from blood samples of 1168 breast cancer cases of T2DM Chinese females were genotyped for three diabetes-related single nucleotide polymorphisms (SNPs) genetic factors FTO rs3751812, IL-6 rs1800796, and HSPD1 rs2605039." (PMID 37510134, 2023).
breast cancer (continued). "TAMs also establish an inflammatory milieu via releasing numerous pro-inflammatory cytokines such as CXCL8 in endometrial cancer, IL6 in breast cancer, and IL1β in pancreatic cancer, which ultimately have correlated with poor prognosis." (PMID 38035101, 2023). "Estrogen deprivation in cultured BM stromal monolayers induces the secretion of IL-6 and IL-8, activates TGFβ and TNFα signaling and promotes the growth of breast cancer colonies." (PMID 37296983, 2023). "Previous studies have reported a synergistic association between IL1Beta, IL-6, and OSM in human breast cancer, which is linked to a poor prognosis." (PMID 38260202, 2023). "One of the mechanisms by which breast cancer cells modulate the immune response is by secreting cytokines such as interleukin 6 (IL-6), which can activate immune cells such as T cells, B cells, and macrophages." (PMID 37174117, 2023). "JGT reduced the Il6 and pSTAT3 expression in mammary tumors; this reduction was observed in malignant tumors for Il6 and in benign tumors for pSTAT3." (PMID 36980301, 2023). "Knocking down PTEN expression in HER2+ breast cancer cells induces trastuzumab resistance through the activation of an IL-6 inflammatory feedback loop." (PMID 36979654, 2023). "Adipose-derived interleukin-6 (IL-6) promoted the proliferation of breast cancer cells by enhancing glutamine metabolism via ASCT2." (PMID 37894450, 2023). "In breast cancer lung metastasis, sevoflurane exposure during surgery primed the lung microenvironment via the IL6/JAK/STAT3 pathway." (PMID 37345096, 2023). "Functionally, tumor exosomal cSERPINE2 was shuttled to tumor associated macrophages (TAMs) and enhanced the secretion of Interleukin-6 (IL-6), leading to increased proliferation and invasion of breast cancer cells." (PMID 36797769, 2023). "The responsiveness of IL-6 signaling in peripheral blood T cells has also been evaluated in breast cancer patients compared to healthy donors." (PMID 37741983, 2023). "The data illustrating that IL-6, IL-8 and the receptors sortilin, IL-6R and IL-6-ST were highly secreted from PDS-adapted breast cancer cell lines support the fact that the PDS model includes a microenvironment promoting the cancer stem cell population." (PMID 38136303, 2023). "Our results identified the IL-6/STAT3 signaling pathway as an important therapeutic target in breast cancer radiotherapy." (PMID 36635302, 2023). "Our results revealed that HSPB1 overexpression promoted the secretion of IL6, whereas HSPB1 knockdown led to decreased IL6 secretion in breast cancer cells." (PMID 37454220, 2023). "Higher blood levels of glucose, lactate, fibrinogen, and IL-6 were found in patients with mammary tumours (p < 0.05)." (PMID 36899784, 2023). "As a steroid hormone with anti-inflammatory effects, estrogen downregulates the levels of IL-6 and gp130 levels in osteoblasts and breast cancer cells, thereby affecting the downstream IL-6/gp130 signaling pathway." (PMID 37828513, 2023). "The IL6/STAT3 pathway hijacked estrogen receptor alpha enhancers to promote cancer cell proliferation in breast cancer." (PMID 37298609, 2023). "We found that the stromal cells in breast cancer tissues were positive for IL-6, suggesting that IL-6 in breast cancer primarily originates from CAFs." (PMID 36635302, 2023). "Many lines of evidence showed that IL-6 is capable of enhancing EMT via JAK-STAT3 signaling in a variety of human cancers such as breast cancer, head and neck squamous cell carcinoma, pancreatic cancer and CRC." (PMID 37047623, 2023). "explained the effect of exercise (HIIT – high impact interval training and general aerobic and resistance exercise) on reducing IL-6 level in breast cancer patients and survivors." (PMID 37181043, 2023). "Another study demonstrated that as well as IL-6, breast cancer secretes TNF-α to stimulate KDM2A expression in normal mammary fibroblasts and transform them into CAFs." (PMID 37496657, 2023).
breast cancer (continued). "Overall, these studies highlight the importance of balanced IL-6 signaling in T cell function and demonstrate the significance of impaired IL-6 signaling in various cancer types, including breast cancer, NSCLC, and HCC." (PMID 37741983, 2023). "A synthetic anti-gp130 compound (bazedoxifene) inhibited IL-6-induced growth of breast cancer cell lines and down-regulated STAT3 phosphorylation." (PMID 36835413, 2023). "The proinflammatory cytokine IL-6, which was reported to progress oncogenesis, exhibited increased expression in breast cancer patients with HPV." (PMID 37519781, 2023). "For example, it was demonstrated that the secretion of interleukin (IL)-6 from CD44+/CD24low/− breast cancer cells is dependent on autophagy and necessary for CSC maintenance." (PMID 36902427, 2023). "Taken together, the results revealed an interplay between progranulin and IL-6/8 in breast cancer, demonstrated not only by an increase in secretion of the proteins but also on the cellular protein levels." (PMID 38136303, 2023). "It has been proposed that IL-6 SNP is related to the prognosis of some cancers such as breast cancer, bladder cancer, neuroblastoma, and non-small cell lung cancer." (PMID 38024543, 2023). "Elevated levels of IL-6 and SerpinE1 were also demonstrated in the case of CAAs related to breast cancer." (PMID 37481560, 2023). "IL-6 was the most frequently mentioned cytokine across all breast cancer studies included in this review." (PMID 37181043, 2023). "Inflammatory factors, such as PGE2 and IL-6 production, increase aromatase activity, accelerate estrogen production, and deteriorate breast cancer." (PMID 36794014, 2023). "Herein, we found that CAF-secreted IL-6 activated the STAT3 signaling pathway to promote breast cancer cell growth and radioresistance." (PMID 36635302, 2023). "After progranulin treatment, IL-6 and IL-8 protein levels increased in both cell lines, validating a progranulin-mediated induction of IL-6 and IL-8 protein levels in breast cancer cells parallel to an increased secretion of the proteins." (PMID 38136303, 2023). "In turn, mammary tumor cells produce IL-6, VEGF, CCL22 to recruit TAMs, which stimulate IL-23 production and maintain the suppressive activity of Treg in the TME." (PMID 36835413, 2023). "HDLs from breast cancer cases in stage IV presented a great ability to reduce IL6 production as compared to controls and other stages of the disease." (PMID 37628945, 2023). "Kynurenic acid (KYNA), a metabolic product of tryptophan, was found to stimulate the expression of IL-6 in human breast cancer cells as well as cytokine production in mouse splenocytes." (PMID 37235428, 2023). "GREM2 inhibited adipogenesis and the production of the adipokines, including IL-6, in adipocytes, which likely makes an important contribution to the inhibition of breast cancer progression." (PMID 37880751, 2023). "Proliferative and invasive abilities of breast cancer cells reduced by adipocytes-Grem2 were restored by IL-6 treatment." (PMID 37880751, 2023). "For example, breast cancer cells secrete pro-inflammatory cytokines such as IL-6 and tumor necrosis factor (TNF-α) that can promote adipose tissue inflammation and disrupt normal adipose tissue function." (PMID 37174117, 2023). "Our study suggests that GREM2 overexpression in adipocytes can inhibit adipogenesis, reduce the expression and secretion of several adipokines, including IL-6, and ultimately inhibit breast cancer progression." (PMID 37880751, 2023). "In this study, we aimed to investigate the function of IL-6 secreted from CAFs on the biological behavior of breast cancer cells." (PMID 36635302, 2023). "CAAs have been proven to secrete more chemokines, including CCL2, CCL5 and IL6, to enhance the metastasis, stemness, angiogenesis, and proliferation of breast cancer cells." (PMID 36632469, 2023).